CRP (C-reactive protein)
Diseases named in the same sentence as CRP in open-access papers (continued):
Sharing a sentence is not in itself a finding about the gene and the disease.
atherosclerosis (continued). "This review will highlight the complex results of genomic, epidemiological, and experimental studies on CRP and will show why further studies investigating the relationship between CRP and atherosclerosis might be needed." (PMID 24808639, 2014). "It is also unlikely that CRP can be a therapeutic target for the treatment of atherosclerosis." (PMID 24872601, 2014). "In fact, elevated CRP levels within coronary plaques may contribute to the development and progression of atherosclerosis: instability of coronary atherosclerotic plaques is the major cause of ACS." (PMID 25192283, 2014). "Neither the meta-analyses nor the JUPITER trial were able to answer the question if CRP is a causal factor in coronary heart disease or just an innocent bystander in inflammation, a well- accepted pathomechanism in atherosclerosis." (PMID 24808639, 2014). "Towards this goal, in collaboration with ISIS Pharmaceuticals, Inc., we designed and injected robust rabbit CRP antisense oligonucleotides into WHHL rabbits, which have elevated plasma CRP levels (10~20-fold higher than in wild-type rabbits) in addition to having atherosclerosis." (PMID 24872599, 2014). "CRP has been used as a marker of inflammation, being a stronger predictor of atherosclerosis." (PMID 23451155, 2013). "CRP in turn may directly affect vasculature facilitating the development of atherosclerosis, and, eventually, cardiovascular diseases." (PMID 23326550, 2013). "After the atherosclerosis model was established, the level of the serum lipids, hs CRP and IL-6 of rabbits in high-cholesterol group and Losartan group increased significantly in comparison with control group(P < 0.05), but there was no statistical difference between the two groups (P > 0.05)." (PMID 25478508, 2013). "Nevertheless, the predictive value of CRP as in atherosclerosis is only moderate." (PMID 23365489, 2013). "The most extensively studied serum biomarker in atherosclerosis is the C-reactive protein (CRP)." (PMID 23365489, 2013). "Originally, CRP was considered to be a nonspecific biomarker of inflammation; however, following ~10 years of investigation, it has been demonstrated that CRP participates in inflammation and atherosclerosis directly and has been indicated to be a prognostic factor and a risk factor." (PMID 24223640, 2013). "The positive feedback loop among L5, CRP, and the LOX-1 receptor may underlie a novel mechanism of endothelial dysfunction and atherosclerosis." (PMID 23950953, 2013). "There are other possible explanations for the association of basal CRP with risk of atherosclerosis rather than as an indicator of immune responsiveness." (PMID 23391158, 2013). "In addition some studies have analyzed the role of IL-6 in the atherosclerosis process as this marker has a concordance with CRP in the inflammatory response." (PMID 23497664, 2013). "In addition of being an important inflammatory biomarker and a risk factor for cardiovascular disease, much evidence indicates that the C-reactive protein (CRP) contributes to the atherosclerosis development process." (PMID 23111890, 2013). "Furthermore, previous studies demonstrated that quercetin decreases the elevated serum level of CRP during progression and regression of atherosclerosis using hypercholesterolemic diet in rabbits." (PMID 23717483, 2013). "N-3 consumption in the form of non-fried fish was associated with lower CRP levels in a cross-section study of the multi-ethnic study of atherosclerosis (MESA) cohort." (PMID 31667003, 2013). "Inflammation is a prominent feature of atherosclerosis, and elevation of CRP levels may be an indicate of subclinical atherosclerotic process." (PMID 23451155, 2013). "Furthermore, CRP has been shown to promote atherosclerosis formation by inducing endothelial cells to produce monocyte chemoattractant protein-1 and to express cell adhesion molecules." (PMID 23950953, 2013).
atherosclerosis (continued). "In addition, vascular biomarkers such as high-sensitivity C-reactive protein (hs-CRP) and cell adhesion molecules have proven to be useful to predict subclinical atherosclerosis." (PMID 22645425, 2012). "A variety of variables (CRP, complement C3, IL-6 and TNF-α) implicated in the regulation of the inflammatory process and, in turn, in the pathophysiology of arthritides, are relevant in the etiology and the development of atherosclerosis." (PMID 23036698, 2012). "In addition, there is overwhelming evidence supporting the pathogenetic role of fibrinogen and CRP in atherosclerosis and their predictive capability for future cerebro- and cardiovascular events in patients with subclinical and clinical atherosclerosis." (PMID 23091306, 2012). "Cross-sectional studies have shown that the severity of inflammatory burden in long-standing RA measured by CRP, as well as disease duration, are associated with increased preclinical atherosclerosis in patients without traditional CVD risk factors." (PMID 22390577, 2012). "Mendelian randomisation studies suggest that two intensively studied biomarkers of inflammation associated with cardiovascular disease, C-reactive protein and fibrinogen, are unlikely to be causally related to atherosclerosis." (PMID 22421340, 2012). "Because MA is associated with CVD and inflammation, carotid intima medial thickness (CIMT) and endothelial function by peripheral arterial tonometry (PAT) as surrogate indices of atherosclerosis and highly sensitive C-reactive protein (hs-CRP) to assess inflammation were measured every six months." (PMID 22363885, 2011). "Moreover, it is a potent inducer of hepatic CRP, a molecule displaying increased levels in patients with severe atherosclerosis and following acute clinical events (myocardial infarction and cerebral ictus)." (PMID 21547256, 2011). "In patients with longstanding RA, CRP could also predict atherosclerosis, as measured by carotid intima media thickness, over an extended follow-up." (PMID 21843325, 2011). "Indeed, CRP has been proposed as a putative clinical biomarker for atherosclerosis serving a possible protective role in the atherogenic process." (PMID 21756316, 2011). "A causal role in disease progression is still possible for CRP if, for example, it were associated with thrombosis and necrosis, rather than the development of atherosclerosis." (PMID 20532236, 2010). "CRP levels predict outcome in healthy individuals and patients with atherosclerosis." (PMID 21187863, 2010). "Moreover, other studies had shown a correlation between PCOS and serum markers of atherosclerosis such as CRP, interleukin-18, homocysteine, and endothelial dysfunction." (PMID 21062435, 2010). "The cross-sectional design does not provide definitive evidence of causality or reverse causality although the results do strongly argue against a detrimental effect of CRP on all aspects of endothelial dysfunction and atherosclerosis, particularly those involving NO availability." (PMID 20436910, 2010). "On the other hand, increased level of CRP has been seen in atherosclerosis." (PMID 22577410, 2010). "It has been hypothesized that anti-CRP antibodies could play a role in lupus-related atherosclerosis." (PMID 20003354, 2009). "It is known that inflammation plays an important role in the development and progression of atherosclerosis, and inflammatory markers such as CRP and WBCs count are strong predictors of cardiovascular events in healthy populations as well as patients with coronary heart disease." (PMID 19187547, 2009). "In contrast to clinical events, an independent association between hs-CRP levels and coronary or carotid atherosclerosis has not been clearly established." (PMID 19421644, 2009). "Although, originally CRP was suggested to be purely a biomarker, recent studies have pointed that it may in fact be a direct mediator of atherosclerosis." (PMID 18764931, 2008).
atherosclerosis (continued). "Several observational studies show high circulating CRP to be associated with increased risk of coronary heart disease (CHD) events and increased carotid intima-media thickness (CIMT), a subclinical marker of atherosclerosis." (PMID 18714381, 2008). "Increasing evidence implicates CRP as a contributor to the pathogenesis of atherosclerosis." (PMID 20157364, 2008). "The authors concluded that CRP is a poor predictor of atherosclerosis disease burden." (PMID 18564201, 2008). "As well-known ligand of phosphorylcholine residues, CRP binds avidly to oxidized low-density lipoproteins and may induce foam cell formation in atherosclerosis." (PMID 18513415, 2008). "CRP, which increases in active disease, may contribute to atherosclerosis because it stimulates macrophages to produce tissue factor, a procoagulant that is found in atherosclerotic plaques." (PMID 16646989, 2006). "CRP activates complement through binding to the Fcγ receptor and enhancing phagocytosis of low-density lipoprotein, leading to the formation of foam cells, thus directly contributing to the development of atherosclerosis." (PMID 16263508, 2005). "An investigation found that in patients who developed atherosclerosis, CRP could better reflect the extent of aortic atherosclerosis compared to coronary arteries, and multivariate analyses showed that the severity of aortic atherosclerosis was an independent factor associated with the level of CRP." (PMID 40779499, 2025). "However, further study with a larger sample size may be required for further understanding of autoimmune disease and the C-reactive protein in relation to atherosclerosis." (PMID 41311771, 2025). "CRP not only reflects systemic inflammatory status but may also exert direct effects on cardiovascular health by promoting endothelial dysfunction and the progression of atherosclerosis." (PMID 40937117, 2025). "The concept that atherosclerosis is a chronic inflammatory disease of the arterial wall gained traction in the 1980s when studies revealed elevated levels of acute-phase proteins, such as C-reactive protein (CRP), in patients with coronary atherosclerotic disease and myocardial ischemia." (PMID 40943241, 2025). "Therefore, it seems prudent to assess CRP and HDL associations at the same time to distinguish healthy individuals from patients with endothelial dysfunction and a risk of cardiovascular diseases, including atherosclerosis." (PMID 39596269, 2024). "Interestingly, serum CRP levels were also found to be elevated in periodontitis patients, while periodontal disease therapy reduced systemic inflammatory markers of atherosclerosis progression, like CRP and interleukins, highlighting the potential systemic benefits of managing oral infections." (PMID 39795606, 2024). "Moreover, low oxygen saturation could potentiate systemic inflammation and oxidative stress, marked by heightened VEGF and CRP expression, thereby fostering atherosclerosis and vascular dysfunction." (PMID 38533418, 2024). "Proinflammatory markers like C-reactive protein (CRP), TNF-alpha, IL-6, plasminogen, endothelin-1, and fibrinogen are increased in patients with IR, which play a vital role in enhancing the risk for increased atherosclerosis and reducing vascular reactivity while impairing endothelial function." (PMID 39634976, 2024). "Furthermore, CRP and IL-6 are described to be elevated in atherosclerosis and therefore the higher levels of CRP and IL-6 in the RA risk group might partly be explained by the underlying atherosclerotic process." (PMID 39012360, 2024). "However, in atherosclerosis CRP levels are usually below 5 mg/L." (PMID 36768404, 2023). "Additionally, the levels of total cholesterol (TC), triglyceride, low density lipoprotein cholesterol (LDL-C), carotid intima-media thickness (CIMT) and C-reactive protein (CRP) in the atherosclerosis group were significantly higher than those in the control group (P < 0.001)." (PMID 36890438, 2023).
atherosclerosis (continued). "The causal effect of CRP on the risk of hypertensive heart disease (HHD) was statistically significant, but we did not observe a significant causal relationship between CRP and the risk of myocardial infarction, coronary artery disease, heart failure, or atherosclerosis." (PMID 37298077, 2023). "In atheroma, a CRP increase stimulates the induction of IL-6 by macrophages, suggesting that CRP may have a direct impact on IL-6 release; yet, an atherosclerosis model found that a combination of oxLDL along with the monomer and the pentamer decreases TNF-α and IL-6 production." (PMID 37873776, 2023). "Aligned with them, we also found that serum TB, CB and UCB levels within the normal reference were negatively associated with CRP in patients with T2DM, which indicated that high-normal bilirubin may exhibit powerful anti-inflammatory activity against lower limb atherosclerosis." (PMID 37208703, 2023). "However, under exacerbated inflammatory states, also mediated by CRP, NO production increases, and along with other reactive oxygen species, can lead to oxidative stress, which in turn, promotes vascular pathologies such as atherosclerosis." (PMID 36834801, 2023). "CRP, a widely studied acute phase protein, may be involved in the pathogenesis of atherosclerosis by activating complement, stimulating monocyte chemotaxis, and inhibiting neutrophil chemotaxis via the classical pathway, and there is increasing evidence that it is a risk factor for atherosclerosis." (PMID 36908593, 2023). "Prior studies have reported that some components of the MedDiet such as nuts may downregulate inflammatory markers related to atherosclerosis, such as serum C-reactive protein (CRP), interleukin 6 (IL-6), cell adhesion molecule-1 (CAM-1), and intercellular adhesion molecule-1 (ICAM-1)." (PMID 35192097, 2023). "Moreover, serum CRP levels and waist circumference could be particularly related to subclinical atherosclerosis and may be indicators of future cardiovascular diseases." (PMID 37198010, 2023). "In middle-aged and older individuals from the general population, higher serum IgA and IgG, but not IgM, are associated with CVD, cardiovascular mortality, and severe atherosclerosis, particularly within Ig reference ranges and independent of serum C-reactive protein." (PMID 36723716, 2023). "Levels of CRP might affect the association between GDF-15 concentrations and atherosclerosis." (PMID 37371667, 2023). "However, it remains uncertain whether CRP is directly involved in the progression of atherosclerosis or simply a consequence of the atherosclerotic process." (PMID 37296402, 2023). "For example, CRP reduces endothelial nitric oxide synthase (eNOS) activity which subsequently reduces vasodilator effects of NO and increases vasoconstrictor effects of Endothelin-1 (ET-1) all of which increases the chances of atherosclerosis and clot formation." (PMID 35192097, 2023). "It has been shown that remnant lipoprotein particles initiate early atherosclerosis, have adverse effects on endothelial functions, are associated with atherogenic small dense LDL, and also with prothrombotic and proinflammatory biomarkers such as Factor VII, PAI-1, and CRP." (PMID 35237643, 2022). "The multiple local inflammatory activities lead to an increased systemic production of C-reactive protein (CRP), tumour necrosis factor-alpha (TNF-α), interleukin (IL)-6 and IL-1, which are also thought to play a causal role in the development and progression of atherosclerosis." (PMID 36003652, 2022). "CRP may contribute directly to the pathogenesis of atherosclerosis." (PMID 36611532, 2022). "Moreover, CRP level is correlated to the endothelial dysfunction and may reflect the development of atherosclerosis." (PMID 36338499, 2022).
atherosclerosis (continued). "Karolkiewicz’s team studied elderly women and found that higher lipid values and CRP levels in healthy overweight and obese women supported the researchers’ hypothesis that weight gain is associated with risk of atherosclerosis regardless of age." (PMID 34769939, 2021). "Although weight loss itself is of potential interest in the atherosclerosis field, it was also shown that rimonabant improved other cardiovascular risk factors, e.g., LDL/high density lipoprotein (HDL) cholesterol ratio, tri-glycerides, and C-reactive protein (CRP)." (PMID 34577636, 2021). "Whether CRP is a marker lacking specificity that is elevated in the inflammatory response or a molecule with direct causal effect in the pathogenesis of atherosclerosis and CAD remains controversial." (PMID 34760045, 2021). "However, the CANTOS trial represented a proof-of-concept that a plasmatic inflammatory biomarker (in that case CRP) can be used for selecting patients with atherosclerosis who may be candidates for immunomodulation therapies." (PMID 33153204, 2020). "We used logistic regression analysis to assess whether rs21007595 polymorphism was independently associated with the progression of atherosclerosis after adjusting for age, waist circumference, tobacco smoking, SBP, DBP, total cholesterol, LDL-C levels, and hs-CRP." (PMID 32284067, 2020). "However, the mechanism linking CRP and the development of atherosclerosis is poorly understood." (PMID 32358950, 2020). "These associations were independent of CRP supporting the hypothesis that PTX3 reflects different aspects of atherosclerosis-related inflammation than CRP." (PMID 32411445, 2020). "In conclusion, plasma biomarkers Lp-PLA2 activity and mass were found to be useful markers of PAD risk during long-term follow-up together with the established biomarker CRP, implying that they might also be used as predictors for subclinical atherosclerosis and atherosclerotic disease." (PMID 30948779, 2019). "Similarly, CRP may be an atheroprotective molecule, as shown by using transgenic CRP in animal models of human like atherosclerosis." (PMID 31114584, 2019). "Two studies found higher CRP levels in SS patients without evidence of significant association with increased risk of atherosclerosis or CV events and higher CRP levels were detected in a Spanish cohort of patients displaying more concomitant classic CV risk factors." (PMID 31110500, 2019). "CRP was also found to suppress the proatherogenic effects of macrophages when bound to lysophosphatidylcholine present in ox-LDL and inhibit the association of ox-LDL to macrophages; this effect may in part retard the progression of atherosclerosis." (PMID 31379851, 2019). "Thus, CRP is a marker of inflammation and atherosclerosis that may play an active role in the atherogenic process." (PMID 29644527, 2018). "The positive correlation between atherosclerosis and inflammation, demonstrated inprevious studies in both general population and hemodialysis patients could also be observed in our study, considering thevariables CRP and serum albumin." (PMID 28443959, 2017). "However, the validity of this biomarker remains unclear as treatment with modified CRP and native CRP have been shown to give opposite effects on atherosclerosis in ApoE(−/−) mice." (PMID 28351393, 2017). "Indeed, CRP may be involved in all stages of atherosclerosis by influencing processes such as the endothelial function, lipid effect, angiogenesis and apoptosis, thrombosis, complement activation, and monocyte recruitment and activation." (PMID 28635634, 2017). "Additionally, LDL apheresis confers other pleiotropic effects protecting patients against atherosclerosis as it decreases the plasma concentrations of several pro-inflammatory markers including cytokines, chemokines, adhesion factors and C-reactive protein, too." (PMID 27756331, 2016). "CRP may be relevant to both infection and sterile inflammation in atherosclerosis." (PMID 27621811, 2016).